PTGS2 (prostaglandin-endoperoxide synthase 2)
Diseases named in the same sentence as PTGS2 in open-access papers (continued):
Sharing a sentence is not in itself a finding about the gene and the disease.
endometriosis (42 papers, 2007 to 2025). The growth of functional endometrial tissue in anatomic sites outside the uterine body. "In addition, PTGS2 polymorphisms are linked to an increased risk of endometriosis, with genetic susceptibility mediated by inflammatory pathways." (PMID 40313549, 2025). "Given the estrogen-dependent and inflammatory nature of endometriosis, we explored two key molecular targets: ERβ and PTGS2." (PMID 41011475, 2025). "Prostaglandin lactone synthase (PTGS2) is a hub gene with significantly upregulated expression in patients with endometriosis, driving prostaglandin synthesis." (PMID 40313549, 2025). "Statistically significant differences were observed in the expression levels of six hub genes (ACSL4, CYP2C18, CYP2C9, HSD17B3, HSDL2, and PTGS2) between the Endometriosis and Control groups of the combined GEO datasets (p < 0.001)." (PMID 40313549, 2025). "Lutz and colleagues showed the reduced expression of PTGS2 in cumulus cells of infertile women with endometriosis." (PMID 36768772, 2023). "Among the top genes in the two key subnetworks, VEGFA, CXCL8, CCL2, IL1B and PTGS2 were also considered to be highly related to endometriosis in MalaCards." (PMID 35130311, 2022). "Moreover, PTGS2 is regulated by various factors, including hormonal therapy, which is a common treatment for endometriosis." (PMID 40313549, 2025). "This may be important as miR-144-3p is predicted to target several factors relevant to the pathophysiology of endometriosis including PTGS2/COX226–28, TNF-α29,30, IL-1β29,30, and IL-630,31." (PMID 31217548, 2019). "Moreover, PTGS2 was shown to be down-regulated in CCs of infertile women with endometriosis." (PMID 30031399, 2018). "MiR-196a may contribute to progesterone resistance in endometriosis and miR-144-3p has been shown to correlate with cell survival status in human endometriotic lesions and is involved in the regulation of inflammatory mediators such as IL-6, IL-1β, TNFα, PTGS2 and COX2." (PMID 39457531, 2024). "It had 15 targets in the endometriosis-related gene set, and some of these targets, such as ESR1, ESR2 and PTGS2, had a high correlation score in MalaCards." (PMID 35130311, 2022).
hepatocellular carcinoma (42 papers, 2008 to 2025). A malignant tumor that arises from hepatocytes. "The majority of DEGs, involved in the pathway “Hepatitis C and Hepatocellular carcinoma”, encode pro-inflammatory proteins (IL-6, IL-8, PTGS2), and, therefore, this term should be also considered as inflammation related." (PMID 31523389, 2019). "NR1I2, ESR1, ALPL, MME, IGF1, NR3C2 and PTGS2 were differentially low expressed in hepatocellular carcinoma tissues." (PMID 38842135, 2024). "Previous studies have shown that the overexpression of PTGS2 is mediated by STAT3, and the inactivation of STAT3 is accompanied by the decreased expression of PTGS2 in hepatocellular carcinoma." (PMID 39125712, 2024). "Studies have shown that EZ from CBC was able to inhibit hepatocellular carcinoma by inhibiting PTGS2 in SMMC-7721 cell." (PMID 34055017, 2021). "Several cancer types, including basal cell carcinoma, hepatocellular carcinoma, non-small cell lung cancer, cutaneous squamous cell carcinoma, and solid tumors, share two common targets: prostaglandin-endoperoxide synthase 2 (PTGS2) and transforming growth factor beta 1 (TGFB1)." (PMID 41041638, 2025). "For instance, PTGS2 is upregulated in adenocarcinoma of the gall bladder, squamous cell carcinoma, cholangiocarcinoma, transitional cell carcinoma, endometrial carcinoma, and hepatocellular carcinoma." (PMID 40643495, 2025). "The results of Western Blot showed that curcumin decreased the expression of ferroptosis-related proteins SLC7A11, GSS, GPX4, and FTH1, as well as increased the expression levels of PTGS2 and ACSL4 in hepatocellular carcinoma tissues." (PMID 39311951, 2024). "Liver anticancer potential for BBR is mainly due to the regulation of hepatoma cells via interactions among ESR1, TB52, PTGS2, CCDN1, and MAPK1 pathways, which act on Hub-nodes in those interlinked pathways." (PMID 34885950, 2021). "Nonsteroidal anti-inflammatory drugs targeting PTGS2 have been shown to inhibit the proliferation of cultured hepatocellular cancer cells by inducing cell-cycle arrest." (PMID 20628618, 2010). "Finally, sinapine thiocyanate from SS significantly decreases the protein expression of PTGS1, PTGS2, Bcl-2, MMP-2 and MMP-9 and increases the protein expression of Bax to prohibit the proliferation, migration and invasion of hepatocellular carcinoma cells in SMMC-7721." (PMID 37124205, 2023).
Obesity (42 papers, 2011 to 2025). Accumulation of substantial excess body fat. "Ptgs2 is involved in inflammation in fat and drives obesity-linked insulin resistance and fatty liver." (PMID 33143653, 2020). "In addition, the protein encoded by PTGS2 gene is indicated to be linked with energy homeostasis and metabolic processes based on a cohort of children presenting with syndromic obesity." (PMID 29132311, 2017). "For example, PTGS2/prostanoids exhibit protective functions by reducing fat accumulation and alleviating adipose tissue dysfunction in obesity or high-fat mice models." (PMID 40474257, 2025). "These small molecules, due to their significant PPARG activation and PTGS2 inhibition, demonstrate novel application potential in obesity treatment." (PMID 39684213, 2024). "Taken together, our molecular dynamics results suggest that OA has binding stability to core targets, especially PPARG, PPARA, and PTGS2, which have very high potential in OA anti-obesity." (PMID 38246999, 2024). "This study underscores the power of the 3DHFC-TRS algorithm in uncovering bioactive compounds from natural sources, such as thunder god vine, and highlights the therapeutic promise of PPARG and PTGS2 as novel obesity-related targets." (PMID 39684213, 2024). "It is reported that the cyclooxygenase -2 (PTGS2) selective inhibitor suppresses the development of NAFLD in a diet-induced obesity rat model." (PMID 36143853, 2022). "A high fat diet fed to C57 mice to mimic obesity induced an upregulation in IL-6, TNFa, and Ptgs-2 gene expression from adipose tissue." (PMID 34631607, 2021). "The IKK/NF-κB pathway is a well-known inflammatory signaling pathway involved in the pathogenesis of obesity, and the two genes-PTGS2 and TLR9 involved in this enrichment term should also be focused." (PMID 29132311, 2017). "Obesity-associated inflammatory genes such as IL1B, IL1ra, IL8, and PTGS2 were also increased by AhR ligands in hMADS cells." (PMID 22262711, 2012). "As we illustrated in network pharmacologic analysis, these compounds might work in combination with other active compounds to attenuate obesity via modulating major targets including PTGS2, ADRB2, and NCOA2." (PMID 36928463, 2023). "DEGs of NAMPT, TLR9, PTGS2, HBD, and PCSK1N might be associated with obesity." (PMID 29132311, 2017). "And up-regulated genes-NAMPT, TLR9, PTGS2, HBD, and PCSK1N might be associated with obesity risk." (PMID 29132311, 2017). "These compounds demonstrated superior binding affinity and specificity toward two key obesity targets, PPARG and PTGS2, suggesting their potential to regulate fat metabolism and mitigate inflammatory responses." (PMID 39684213, 2024). "In this study, we thoroughly investigated the potential of small molecules extracted from the thunder god vine (Tripterygium wilfordii) for obesity treatment, with a particular focus on their activating effects on PPARG and inhibitory effects on PTGS2." (PMID 39684213, 2024). "PTGS2 and TNFAIP3 were identified as hypomethylated-high-expression genes and FBXL20 as a hypermethylated-low expression gene in SAT of individuals with obesity." (PMID 37252693, 2023). "Increased expression in mRNA levels with specific markers, e.g., prostaglandin-endoperoxide synthase 2 (PTGS2), have been found in HFD-induced Obesity." (PMID 35937803, 2022). "Molecular docking results also revealed that the hub target genes bound to melatonin with high affinity, particularly AKT1, PTGS2, and ERBB2, can be used to treat LR-induced obesity by melatonin." (PMID 35937803, 2022). "On the other hand, prostaglandin-endoperoxide synthase 2 (PTGS2), cyclin D1 (CCND1), and TFF1 (an ESR1 target gene) were elevated in rFNAs from postmenopausal women with obesity." (PMID 34485137, 2021). "Active ingredients in WP, such as oxidized glutathione, may improve symptoms of HFD-induced obesity by acting on targets such as EGFR, NOS3, MMP2, PLG, PTGS2, and AR." (PMID 38162665, 2023).
Obesity (continued). "Similarly, PTGS2(prostaglandin-endoperoxide synthase 2) and CYP19A1(cytochrome P450 family 19 subfamily A member 1) are also predicted to be pivotal target for reducing or reversing hyperlipidemia and obesity." (PMID 38246999, 2024). "We considered the three most connective nodes as hub-bottleneck genes: prostaglandin-endoperoxide synthase 2 ( PTGS2 ), tumor necrosis factor α-induced protein 3 ( TNFAIP3 ), and F-box and leucine rich repeat protein 20 ( FBXL20 ), which might play a critical role in obesity." (PMID 37252693, 2023). "In individuals living with obesity, 13-HODE was positively correlated with the expression of PTGS2, and PGD3 was positively correlated with PTGS1 and negatively correlated with PTGS2." (PMID 35247847, 2022). "The core targets between estrogen and obesity are proto-oncogene, non-receptor tyrosine kinase (SRC), estrogen receptor 1 (ESR1), prostaglandin-endoperoxide synthase 2 (PTGS2), nuclear receptor subfamily 3 group C member 1 (NR3C1) and cytochrome P450 family 19 subfamily A member 1 (CYP19A1)." (PMID 39575382, 2024).
Sepsis (42 papers, 2012 to 2025). Sepsis is defined as life-threatening organ dysfunction caused by a dysregulated host response to infection. "Collectively, these findings indicate that ACSL4, GPX4, and PTGS2, along with IL-6, hold significant diagnostic and prognostic value in sepsis." (PMID 40264754, 2025). "The diagnostic potential of PTGS2 highlights the important role of ferroptosis markers in the diagnosis of sepsis." (PMID 40264754, 2025). "PTGS2 demonstrated strong diagnostic performance for sepsis (AUC = 0.8771) and was effective in differentiating sepsis patients from non-sepsis patients (AUC = 0.6688, 95% CI: 0.56–0.78, p-value = 0.007)." (PMID 40264754, 2025). "In a mouse model of sepsis induced by LPS, LPS administration upregulated the expression of markers associated with iron-triggered damage, such as prostaglandin endoperoxide synthase 2 (PTGS2), malondialdehyde (MDA), and lipid ROS." (PMID 38161332, 2023). "In addition to Ptgs2 as a recognized biomarker in sepsis-induced cardiac injury, Hmox1 and Slc7a11 were reported as ferroptosis-associated targets in sepsis cardiac dysfunction." (PMID 37424906, 2023). "Furthermore, human and animal models of myocardial diseases show that Ptgs2 expression is associated with cardiac tissue damaged by infarction, septicemia and inflammatory heart diseases." (PMID 34445793, 2021). "Similarly, elevated ACSL4 and PTGS2 in ICU sepsis patients are associated with heightened IL-6, IL-8, procalcitonin, as well as high-sensitivity C-reactive protein, demonstrating strong diagnostic performance for sepsis along with its inflammatory complications." (PMID 41250137, 2025). "Significant differences in PTGS2 expression were observed between sepsis patients and healthy individuals (p-value < 0.0001), as well as between sepsis and non-sepsis patients (p-value < 0.001)." (PMID 40264754, 2025). "PTGS2, a key enzyme in prostaglandin synthesis, is significantly upregulated in sepsis, promoting the production of the inflammatory mediator PGE2." (PMID 41252417, 2025). "For differentiating sepsis from non-sepsis in ICU patients, IL-8, ACSL4, GPX4, CRP, PCT, NEU%, IL-6, and PTGS2(p-value =0.007) exhibited significant diagnostic value (all p-value <0.00001)." (PMID 40264754, 2025). "Consistent with the results from the transcriptomics datasets on human cardiac tissues, sepsis increased Comt and Ptgs2 mRNA levels and decreased Ppara and Pparg mRNA levels." (PMID 38641695, 2024). "In an in vitro assay, PBA effectively inhibited sepsis-induced reductions in Comt, Ptgs2 and Ppara after sepsis." (PMID 38641695, 2024). "The Comt, Ptgs2 and Ppara, were demonstrated as key genes to modulate amino acid metabolism and lipid metabolism to play a protective role on cardiac function in sepsis." (PMID 38641695, 2024). "PBA protects sepsis-induced cardiac injury by targeting Comt/Ptgs2/Ppara, which regulates amino acid metabolism and lipid metabolism." (PMID 38641695, 2024). "The results demonstrated a marked decrease in the expression of GPX4 and SLC7A11, while PTGS2 expression was significantly increased in liver tissues of the septic mice, suggesting that sepsis induces ferroptosis in liver tissues." (PMID 39512683, 2024). "In the present study, we reveal the protective role of LCN2 in SILI in CLP model of sepsis by attenuating PTGS2-dependent ferroptosis." (PMID 39512683, 2024). "In order to further investigate the role of Ptgs2, Hmox1, and Slc7a11 in sepsis-induced cardiac injury, we first investigated their expression levels in each group." (PMID 37424906, 2023). "In fact, numerous studies have consistently highlighted the significant role of ferroptosis in the development of sepsis-induced heart injury, and Ptgs2, Hmox1, and Slc7a11 are well-recognized ferroptosis-associated targets by academia." (PMID 37424906, 2023).
Sepsis (continued). "In the mouse model of sepsis, LPS treatment significantly induced the expression of PTGS2 and SLC7A11, and upregulated the levels of iron and MDA in lung tissues, while Pyk2 inhibitor TAE226 decreased these positive markers of ferroptosis." (PMID 37886006, 2023). "The fold change of Ptgs2, Hmox1, and Slc7a11 in sepsis-induced heart injury increased in 24 h and decreased in 48 and 72 h, which exhibited the same time trend as found previously." (PMID 37424906, 2023). "Based on degree centrality, 27 hub genes were selected, in which six genes (MMP9, CD44, EGR1, ACTN2, TNNT3, and PTGS2) were selected on the basis of a multi-network variable selection approach and validated in a well-established sepsis mice model." (PMID 35205254, 2022). "In the present study, we found that PTGS2 was upregulated during sepsis, and Fer-1 treatment markedly decreased PTGS2 expression in the heart." (PMID 34787054, 2021). "The higher expression level of cyclooxygenase-2 (COX-2), also known as prostaglandin endoperoxide synthase 2 (PTGS2) – a recognized marker of ferroptosis – was observed in the heart of murine model with sepsis." (PMID 33869204, 2021). "DEX could attenuate AKI through KDM5A inhibition in sepsis, transcription and protein levels of genes such as TLR4, MYD88, MTA1, PTGS2, CASP3 associated with NF-κB signaling pathway were all compromising after treated with DEX." (PMID 40989844, 2025). "So, we hypothesized that PBA may induce a series of beneficial metabolic changes through the regulation of the immune microenvironment of sepsis by PTGS2, COMT and PPARA." (PMID 38641695, 2024). "In LPS-induced sepsis mouse models, it has been observed that LPS elevates the levels of ferroptosis-related markers, including prostaglandin-endoperoxide synthase 2 (PTGS2), malondialdehyde (MDA), and lipid ROS, which subsequently leads to ferroptosis and mitochondrial damage." (PMID 39544947, 2024). "In addition, the time-course expressions of Ptgs2, Hmox1, and Slc7a11 in the model of sepsis-induced cardiac injury induced by the injection of LPS were also analyzed." (PMID 37424906, 2023). "While Ptgs2 has been previously reported to be involved in the regulation of septic cardiomyopathy, this study is the first to demonstrate that downregulation of Hmox1 and Slc7a11 can alleviate ferroptosis in sepsis-induced cardiac injury." (PMID 37424906, 2023). "However, few studies have investigated serum PTGS2 levels in sepsis patients." (PMID 40264754, 2025). "However, the upregulation of PTGS2 can also be observed under various inflammatory conditions, suggesting its potential as a biomarker for early diagnosis, treatment, and prognosis evaluation of sepsis." (PMID 40264754, 2025). "Then, network pharmacology screening revealed EGFR, PTGS2, SRC and ESR1 as the top four overlapping targets in a PPI network, and GO and KEGG analyses revealed the top 20 enriched biological processes and signalling pathways associated with the therapeutic effects of acacetin on sepsis." (PMID 34483900, 2021). "Dot plot visualization further confirmed these trends at the gene level, with C3, SERPING1, and HLA-A/B/C being notably upregulated in Astrocyte 2 under sepsis conditions, while EMP1, CLCF1, and PTGS2—representing A2 features—were similarly elevated." (PMID 41030458, 2025). "In this study, we detected the serum levels of ACSL4, GPX4, and PTGS2 in ICU sepsis patients, non-sepsis patients, and healthy individuals." (PMID 40264754, 2025). "Western blot analysis of ferroptosis-related proteins revealed that sepsis altered the expression of 4-HNE, FTH1, GPX4, ACSL4, PTGS2, and SLC7A11, which was reversed by ghrelin and Fer-1, indicating their role in inhibiting ferroptosis." (PMID 39857660, 2024). "In patients died from sepsis, the expression levels of COMT and PTGS2 were significantly elevated, PPARA and PPARG were significantly decreased." (PMID 38641695, 2024).
Sepsis (continued). "We found that relative to uninfected controls, human neonates with clinical sepsis exhibited significantly reduced expression of ALOX15, PTGS2 and CYP2J2, implicating all main AA metabolic pathways in sepsis." (PMID 38769383, 2024). "As a well-recognized marker of ferroptosis, Ptgs2, also known as cyclooxygenase-2 (COX-2), has shown a high level of expression in sepsis-induced cardiac injury." (PMID 37424906, 2023). "GO and KEGG analyses were performed, and the core targets of EGFR, PTGS2, SRC and ESR1 were input into the Omicshare database to identify the possible mechanism by which acacetin affects sepsis." (PMID 34483900, 2021). "All potential targets of acacetin and sepsis were methodically obtained, and the top four overlapping targets in the PPI network were EGFR, PTGS2, SRC and ESR1." (PMID 34483900, 2021). "A PPI network of the 49 common targets between acacetin and sepsis was constructed based on degree value screening, and EGFR, PTGS2, SRC and ESR1 were identified as the core targets." (PMID 34483900, 2021). "In this cohort study, serum PTGS2 levels were measured in sepsis patients, non-sepsis patients, and healthy individuals." (PMID 40264754, 2025). "Moreover, in in vitro sepsis model, LCN2 overexpression notably ameliorated LPS-induced cell injury, oxidative stress, and ferroptosis by inhibiting PTGS2 expression." (PMID 39512683, 2024). "However, the observed mRNA upregulation of ferroptosis-related factors, including Ptgs2, Hmox1 and other genes at this early time point, could represent an initial cellular response to oxidative stress, inflammation, or disrupted iron homeostasis triggered by sepsis." (PMID 39726718, 2024). "Baseline serum levels of ACSL4, GPX4, PTGS2, CL-11, IL-6, IL-8, PCT, and hs-CRP significantly differed among sepsis, non-septic, and healthy individuals (all p-value < 0.01)." (PMID 40264754, 2025).